BTNL3 (butyrophilin like 3)
Synonyms: BTNLR; BTN9.1
Tractability: Antibody: UniProt predicts a signal peptide or a membrane-spanning region.
Gene: Protein-coding gene on chromosome 5 (180,988,846 to 181,006,727, forward strand). Ensembl gene ENSG00000168903.
Subcellular location: Membrane
Gene Ontology:
Molecular function: protein binding; signaling receptor binding
Biological process: extrathymic T cell selection; regulation of cytokine production; T cell receptor signaling pathway
Cellular component: external side of plasma membrane; membrane
Genetic constraint (gnomAD): Loss-of-function variants: 22 observed, 36.94 expected, observed/expected ratio (o/e) 0.6, 90% interval 0.43 to 0.85. The upper end of that interval is the gene's LOEUF score, 0.85, which puts it in group 3 of 6, group 1 being the genes least tolerant of losing a copy. Missense variants: 446 observed, 574.71 expected, observed/expected ratio (o/e) 0.78, 90% interval 0.72 to 0.84. Synonymous variants: 179 observed, 217.5 expected, observed/expected ratio (o/e) 0.82, 90% interval 0.73 to 0.93.
Homologues: Orthologues: chimpanzee BTNL3 (92% identical). Paralogues in human: BTNL8 (74% identical), BTNL9 (37% identical), BTN1A1 (35% identical), BTN2A1 (35% identical), BTN2A2 (35% identical), BTN3A3 (34% identical), BTN3A1 (34% identical), ERMAP (27% identical), BTNL2 (22% identical), BTN3A2 (19% identical), CD276 (15% identical), MOG (14% identical), and 3 more.
Diseases named in the same sentence as BTNL3 in open-access papers:
BTNL3 is named in the same sentence as 19 diseases in open-access papers, as found by Europe PMC text mining. Sharing a sentence is not in itself a finding about the gene and the disease. The quoted sentences say what the papers report.
colon cancer (5 papers, 2016 to 2023). "Although there is little known about the functional role of BTNL3, its downregulation was reported in colon cancer alongside BTNL8." (PMID 32375678, 2020). "The modulation of other BTN/BTNL molecules such as BTNL3/BTNL8 seems also of interest in other pathologies such as colon tumors or autoimmune diseases." (PMID 30050536, 2018). "BTNL3 is expressed at steady state by the intestinal epithelium but is markedly downregulated in colon cancer whilst EPCR, a stress-induced MHC class I-like molecule, is frequently overexpressed in multiple cancers including colon cancer." (PMID 37311978, 2023). "Indeed, HNF4G expression, not HNF4A, correlated with BTNL3/BTNL8 expression and γδ T-cell infiltration into tumors in our human colon cancer dataset." (PMID 37309673, 2023).
inflammatory bowel disease (5 papers, 2017 to 2025). A spectrum of small and large bowel inflammatory diseases of unknown etiology. "The potential clinical significance of such interactions is emphasized by recent findings regarding human null alleles of BTNL3, which have been suggested to associate with increased susceptibility to certain forms of inflammatory bowel disease." (PMID 40181561, 2025). "Recent studies have shown the expression of BTNL3 in tumors and its correlation with patient prognosis, immune response, and inflammatory bowel disease." (PMID 32655399, 2020). "The recently discovered role of BTNL3 and BTNL8 for shaping Vγ4 γδ T cells in the human gut might be relevant for the loss of mucosal barrier function in inflammatory bowel diseases." (PMID 28649364, 2017). "Consistent with the recent studies, the role of BTNL3 in the homing and maintenance of a semi-activated state on Vγ4 + γδ T cells in the human gut might be relevant for the onset of gut autoimmune diseases such as ulcerative colitis and inflammatory bowel disease." (PMID 32655399, 2020).
breast carcinoma (4 papers, 2017 to 2022). "BTNL2, BTNL3, BTNL8, BTNL9, and SKINTL constitute the BTNL family, which regard as a tumor inhibitor in many cancers, such as malignant melanoma and breast cancer." (PMID 36034784, 2022).
celiac disease (3 papers, 2019 to 2023). An autoimmune genetic disorder with an unknown pattern of inheritance that primarily affects the digestive tract. "The potential pathophysiologic significance of the Vγ4+ T cell subset was highlighted recently by a report that disruption of the Vγ4+-BTNL3.8 axis is pathognomonic for celiac disease." (PMID 31628053, 2019). "Interestingly, recent studies in patients with celiac disease have demonstrated a reduction in BTNL3/BTNL8 expression following acute episodes of inflammation, with an associated loss of the physiological normal gamma/delta T-cell subset of gut intraepithelial lymphocytes." (PMID 36300623, 2022). "In this respect, it is challenging to understand the claim that a Vγ4+ TCR identified in a celiac disease gut failed to respond to BTNL3-expressing cells." (PMID 31628053, 2019). "Second, it was reported that whereas decreased BTNL3 and ablated BTNL8 expression in celiac disease could renormalise, this did not correlate with renormalisation of either intestinal Vγ1+ cells or TRGV4 reads, which is also consistent with other factors contributing to the cells’ dysregulation." (PMID 37708268, 2023).
Crohn disease (3 papers, 2023 to 2024). A gastrointestinal disorder characterized by chronic inflammation involving all layers of the intestinal wall, noncaseating granulomas affecting the intestinal wall and regional lymph nodes, and transmural fibrosis. "Indeed, a common hypomorphic variant allele fusing BTNL8 and BTNL3 is associated with disease-modifying exacerbation of Crohn’s disease, consequent to dysregulation of gut Vγ4+ cells." (PMID 39576310, 2024). "Moreover, CD103+Vγ4+cell dysregulation and loss were also displayed by humans with germline BTNL3/BTNL8 hypomorphism, which we identified as a risk factor for penetrating Crohn’s disease." (PMID 37708268, 2023).
colorectal cancer (1 paper, 2025). A primary or metastatic malignant neoplasm that affects the colon or rectum. "While Vγ4–EPCR binding can be inhibited by the markedly higher binding affinity of Vγ4 to BTNL3, BTNL3 is significantly downregulated in colorectal cancer (CRC) whereas EPCR is commonly overexpressed in CRC and multiple other cancers." (PMID 40148988, 2025).
glioma (1 paper, 2022). A benign or malignant brain and spinal cord tumor that arises from glial cells (astrocytes, oligodendrocytes, ependymal cells). "Because the basal expression levels of BTN1A1, BTNL2, BTNL3, and BTNL8 were relatively low, in further analysis, we only focused on the expression of BTN2/3 subfamilies in pan-gliomas." (PMID 36033440, 2022).
intrauterine growth restriction (1 paper, 2022). "BTNL3 has also been reported to have a possible role in intestinal metabolism and inflammation in neonates with intrauterine growth restriction." (PMID 35651912, 2022).
preeclampsia (1 paper, 2022). Preeclampsia is a hypertensive disorder of pregnancy that is characterized by new-onset hypertension with proteinuria presenting after 20 weeks of gestation, and depending on mild or severe forms may initially present with severe headache, visual disturbances, and hyperreflexia. "The aberrant copies of APOBEC3A, APOBEC3A_B, BTNL3, and LMF1 between preeclampsia patients and controls were verified by quantitative polymerase chain reaction." (PMID 35651912, 2022).
T cell deficiency (1 paper, 2023). "These considerations notwithstanding, our genetic analysis was still able to identify a significant association of BTNL3+BTNL8 / Vγ4+ T cell deficiency with penetrating CD." (PMID 37708268, 2023).
cancer (4 papers, 2012 to 2025). A tumor composed of atypical neoplastic, often pleomorphic cells that invade other tissues. "The distal 5q35.2q35.3 contains the homeobox MSX2, MGAT1 and BTNL3 respectively involved in embryonic development and cancer." (PMID 22253721, 2012). "However, analysis of genomic information from multiple non-cancer cohorts showed that both the NEGR1 promoter deletion and the BTNL3–8 deletion were CNVs occurring at high frequencies in the general population." (PMID 32375678, 2020).
tumor (3 papers, 2021 to 2023). "BTNL3 expression levels were higher in normal tissue than tumor tissue in both the datasets, whereas BTNL8 expression was only higher in normal tissue in the Skrzypczak dataset." (PMID 37309673, 2023). "Both HNF4A and HNF4G were reduced in tumor tissue from both datasets, mirroring reduced BTNL3 and BTNL8 expressions in human tumors." (PMID 37309673, 2023). "We interrogated two human gene expression datasets, The Cancer Genome Atlas (TCGA) and Skrzypczak, to determine whether the expression levels of BTNL3 or BTNL8—homologs of mouse Btnl1 and Btnl6—were different between normal gut and tumor tissues." (PMID 37309673, 2023).
genetic disorders (1 paper, 2025). "Among the prioritized custom CMA genes in the smallest custom CMA NDDi, KIAA1586, ASCL3, BTNL3, SIRPB1, and GLT1D1 exhibit high average shortest path length and low proximity, indicating vulnerability to genetic disorders." (PMID 40869915, 2025).
BTNL3 also shares sentences with these, for which no sentence is quoted: ulcerative colitis (3 papers); autoimmune disease (1); breast tumor (1); infection (1); malignant melanoma (1); metabolic syndrome (1).